CD47 (CD47 molecule)
Diseases named in the same sentence as CD47 in open-access papers (continued):
Sharing a sentence is not in itself a finding about the gene and the disease.
melanoma (continued). "The CD47-SIRPα axis is a master regulator of macrophage-mediated immune evasion in melanoma." (PMID 40861441, 2025). "Therefore, we evaluated CD47 expression in both mouse melanoma models, SM1 and B16F10 (abbreviated B16)." (PMID 38414061, 2024). "Therefore, the novelty of the present study relies on the use of HDAC6i to control the CD47/SIRPα axis by modulating their expression in melanoma cells and macrophages, respectively." (PMID 38414061, 2024). "Furthermore, HDAC6is such as Nexturastat A (NextA) downregulate SIRPα on macrophages and modulate CD47 expression in melanoma cells." (PMID 38414061, 2024). "In addition, HDAC6 inhibition diminished the expression of SIRPα, increased the expression of other pro-phagocytic signals in macrophages, and downregulated CD47 expression in mouse and human melanoma cells." (PMID 38414061, 2024). "Conversely, the BRAFV600E inhibitor vemurafenib increased CD47 expression in melanoma cells." (PMID 39201643, 2024). "Interestingly, CD47-induced radiosensitivity is specific to healthy tissues, as inhibiting CD47 in mice bearing melanoma or squamous lung tumors prior to irradiation significantly reduces tumor growth." (PMID 39039207, 2024). "Therefore, our studies support the rationale for combining HDACis and anti-CD47 to treat melanoma, as this combination targets both the receptor and the ligand of the CD47/SIRPα axis." (PMID 38414061, 2024). "As T cells and CAFs, the main source of CD47 in the melanoma model, are predominantly located at the tumor edge along the boundary with healthy tissue, it is likely that engagement of CD47 by myeloid cells occurs as the cells first enter the tumor before they penetrate the core." (PMID 38577107, 2024). "In this report, we performed ATAC-Sequencing on patient-derived melanoma cells, as well as, the analysis of ATAC-Seq datasets covering clinical melanoma samples to demonstrate a significant increase in chromatin accessibility for the CD47 promoter region in comparison to normal cells and tissues." (PMID 39742254, 2024). "Therefore, after assessing the modulatory role of HDAC6 on macrophage phenotype, we evaluated the effects of HDAC6 inhibition in modulating the CD47/SIRPα axis in melanoma cells and macrophages." (PMID 38414061, 2024). "Moreover, the association between CD47, TSP1, and integrin ανβ3 promotes the vitronectin-associated spread of melanoma cells by activating focal adhesion kinase (FAK), paxillin, and Gi signaling." (PMID 39039207, 2024). "Determining whether specific isoforms of MYCN play direct roles in the CD47-dependent regulation of other immune regulators in CD8 cells in vitro or in melanomas will require further study." (PMID 36768931, 2023). "However, the frequency and effector phenotypes of Cd47−/− CD8+ T cells were constrained in chronic LCMV-infected as well as in mice bearing B16 melanoma tumors." (PMID 36105746, 2022). "The silencing of CD47 by siRNA inhibits melanoma growth and its lung metastases." (PMID 36611344, 2022). "Furthermore, recent data reported resistance under CD47 blockade both to phagocytosis in melanoma and to chemotherapy-induced senescence, highlighting additional obstacles for an anti-CD47 strategy." (PMID 34638503, 2021). "Similarly, anti-CD47 antibody synergizes with PD-L1 blockade for cancer immunotherapy in B16F10 melanoma tumor model." (PMID 34512146, 2021). "It has also been reported that inhibition of CD47 or SIRPα with antagonistic antibodies enhances the phagocytic activity of TAMs and suppresses tumor growth in preclinical models of glioblastoma, melanoma, lymphoma, and breast and colorectal cancer." (PMID 34573091, 2021). "Silenced CD47 in T cells leads to enhanced T cell killing in irradiated melanoma cells." (PMID 34512146, 2021). "Furthermore, in vivo treatment of melanoma tumors not only reduced tumor burden but also modulated CD47 expression." (PMID 33540720, 2021).
melanoma (continued). "Like the observation in the EG7 model, B16F0 melanoma growth was significantly delayed in mice vaccinated (i.s.)with anti-CD47 Ab-coated irradiated B16F0 cells compared to those vaccinated with irradiated B16F0 cells or medium, although to a lesser extent than CD47KO tumor-vaccinated mice." (PMID 31996683, 2020). "The hNVs block CD47-SIRPα signaling axis while promoting M2-to-M1 repolarization within tumor microenvironment, significantly preventing both local recurrence and distant metastasis in malignant melanoma models." (PMID 32999291, 2020). "Here we show that in both mouse melanoma and lymphoma models, strong and specific antitumor immune responses were induced by injection of CD47-deficient, but not CD47-competent, tumor cells or TA-expressing normal cells." (PMID 31996683, 2020). "CD47 expression in human melanoma regulates NK cell function." (PMID 32939931, 2020). "With the use of mouselymphoma and melanoma models, we demonstrated that elimination of CD47 expression from tumor antigen-expressing normal cells or tumor cells by genetic deletion or antibody blocking significantly improved the effectiveness of whole tumor cell vaccination." (PMID 31996683, 2020). "We discovered that inactivated CD47-depleted mouse melanoma cells can protect mice from melanoma." (PMID 31882679, 2019). "Indeed, an anti-CD47 nanobody that inhibits the CD47-SIRPα interaction synergized with a PD-L1 antagonist significantly reducing the growth of tumors in mice previously injected with melanoma cells." (PMID 31921125, 2019). "Interestingly, loss of BNIP3 reduced the expression of CD47 both in normoxic and hypoxic conditions while macrophage phagocytosis and chemotaxis were accentuated only when BNIP3KD melanoma cells were exposed to hypoxia." (PMID 29707136, 2018). "Therefore, the region between -272 and -191 is required for transcriptional upregulation of CD47 in melanoma cells by vemurafenib." (PMID 29050218, 2017). "Indeed, targeting CD47 has demonstrated potent preclinical activity against various cancers including melanoma." (PMID 29050218, 2017). "Moreover, activation of ERK was also important for the increased expression of CD47 in melanoma cells that acquired resistance to vemurafenib in vitro and in vivo." (PMID 29050218, 2017). "Our results now suggest that NRF-1 may play a part in protection of melanoma cells from the immune system through CD47." (PMID 29050218, 2017). "Similarly, melanoma cells selected for resistance to the BRAF inhibitor vemurafenib expressed higher levels of CD47." (PMID 29050218, 2017). "Indeed morpholino suppression of CD47 expression was shown to markedly increase radiation-induced delay in tumor growth considering two syngeneic models of melanoma and squamous cell carcinoma." (PMID 26578962, 2015). "Furthermore, delivery of anti-CD47 siRNA by nanoparticles inhibited melanoma tumor growth and lung metastasis." (PMID 26554307, 2015). "Studies in other cell types, including kidney podocytes and melanoma cells, suggested that SIRPα maintains tyrosine phosphorylation in the cytoplasmic domain and association with SHP-(1/2); cell surface CD47 ligation, on the other hand, triggers SIRPα dephosphorylation and releases SHP proteins." (PMID 24143245, 2013). "Our results demonstrate that in both freshly resected melanoma samples, as well as, in melanoma patient-derived cell lines, the DNA region corresponding to the CD47 promoter has a significantly increased chromatin accessibility which could be conjectured as a sign of active mRNA transcription." (PMID 39742254, 2024). "Interestingly, binding sites for MYC TF were also identified in our analysis of CD47 proximal promoter region, however, MYC binding was undetectable in human malignant melanoma within CD47 DNA promoter region between -120bp to +54 relative to TSS required for its activation." (PMID 39742254, 2024). "However, CD47 blockade has shown modest results in solid tumors, including melanoma." (PMID 38414061, 2024).
melanoma (continued). "Interestingly, we found that the combination of NextA and anti-CD47 decreased tumor growth in SM1 melanoma-bearing mice, increased total immune cell infiltration in the TME, and altered the immune cell composition compared to the single treatment arms, mostly modulating macrophages and NK cells." (PMID 38414061, 2024). "To determine whether this mechanism can account for an increased CD47 mRNA production during melanomagenesis, we performed in-silico analysis of H3K4Me3 histone modifications at the CD47 promoter in melanoma patients and normal adult melanocytes using the GSE33930 dataset." (PMID 39742254, 2024). "In addition, we found that HDAC6i repressed IFNγ-mediated upregulation of CD47 in mouse and human melanoma cell lines through an unknown mechanism." (PMID 38414061, 2024). "In our present work, we used numerous clinical human melanoma samples, as well as, previously collected pathological datasets of disease progression to establish that the tumor-specific upregulation of myeloid checkpoint molecule, CD47, occurs at the mRNA level during melanomagenesis." (PMID 39742254, 2024). "Importantly, we were able to detect strong peak signals associated with an open chromatin structure around the promoter of CD47 in malignant melanomas, which were missing in normal adult melanocytes indicating the closed chromatin structure of the CD47 DNA promoter region in non-transformed cells." (PMID 39742254, 2024). "However, B16 melanomas grew faster in cd47−/− than in WT mice." (PMID 33925464, 2021). "We observed that melanoma cells from all three species displayed unexpected resistance to phagocytosis that could not be fully mitigated by blockade of the ‘don’t eat me’ signal CD47 or by chemotherapeutic enhancement of known ‘eat me’ signals." (PMID 31205227, 2020). "So these results suggest that NRF-1-mediated regulation of CD47 expression is a novel mechanism by which ERK signalling promotes the pathogenesis of melanoma, and that the combination of CD47 blockade and BRAF/MEK inhibitors may be a useful approach for improving their therapeutic efficacy." (PMID 29050218, 2017). "Moreover, pGL3-CD47-(−272/+10) but not pGL3-CD47-(−191/+10) displayed greater transcriptional activity in Mel-CV.S than Mel-CV cells, and in melanoma cells from a post-treatment primary culture with increased CD47 expression compared with those from the paired pre-treatment culture." (PMID 29050218, 2017). "Furthermore, ERK1/2 knockdown also reduced the constitutive expression of CD47 in melanoma cells." (PMID 29050218, 2017). "We therefore propose a model that the reduction in TIL numbers after the initial increase may involve the lack of antigen presentation to T cells by antigen presenting cells (APCs), which fail to capture antigens due to inhibition of their phagocytic activity by increased CD47 in melanoma cells." (PMID 29050218, 2017). "Having demonstrated the functional significance of CD47 upregulation in protection of vemurafenib-resistant melanoma cells from macrophage phagocytosis, we focused on investigating transcriptional mechanisms responsible for vemurafenib-triggered upregulation of CD47 in melanoma cells." (PMID 29050218, 2017). "In human melanoma models, the peptide-PNP system competitively inhibited CD47-SIRPα interactions, thereby unleashing macrophage phagocytosis of tumor cells." (PMID 40861441, 2025). "Compared with CAR-Ms and oAd-CD47 monotherapy, this combination therapy (C + o) achieved superior antitumor efficacy in the CT26 and B16 melanoma mouse models, as well as in the ID8 peritoneal metastasis model." (PMID 40814015, 2025). "B16-F10 melanoma, KPC pancreatic ductal adenocarcinoma, and ID8 ovarian cancer cells were infected at an MOI of 0.1 or 1, and surface expression of CD47 and CRT was evaluated at 6, 12, 24, and 48 h post-infection." (PMID 41322194, 2025).
melanoma (continued). "Honokiol transfersomes also alleviated the immunosuppressive properties of B16F10 melanoma through regulation of TGF-β signalling and reduction of the expression of the CD47 signal (in vitro)." (PMID 40943669, 2025). "They limited the expression of the stem cell marker CD133 (Promitin-1) and the level of CD47, CD133, and TGF-β ameliorating immunosuppressant properties of melanoma stem cells." (PMID 40943669, 2025). "The anti-tumor efficacy of CAR-Ms combined with oAd-CD47 (C + o) treatment was evaluated in vivo using two tumor-bearing mice models: CT26 colon cancer subcutaneous tumor model and the B16 melanoma subcutaneous tumor model." (PMID 40814015, 2025). "Lastly, to evaluate the antitumor activity of Nexturastat A in combination with anti-CD47 or anti-SIRPα antibodies, we performed in vivo studies using the SM1 and/or B16F10 melanoma mouse models." (PMID 38414061, 2024). "To validate these changes in the chromatin landscape of the CD47 promoter region during melanomagenesis, we performed ATAC-seq on multiple independent patient-derived melanoma cell lines in comparison to normal adult melanocytes." (PMID 39742254, 2024). "In this context, a recently reported dual inhibitor of CD47/SIRPα and TIGIT/PVR pathways merits further study for utility as an ICI in melanoma." (PMID 36768931, 2023). "Accordingly, nicotine exposure increased CD47 levels in lung cancer cell lines and PDL1 in lung cancer and melanoma cell lines." (PMID 37566079, 2023). "Interaction of CD47 and TSP-1 blocked the escape of breast and colorectal cancer cells from chemotherapy-induced senescence and sensitized melanoma cells to radiotherapy in a cell autonomous manner." (PMID 37958404, 2023). "Studies in melanoma and breast tumors found that TSP-1 overexpression in cancer cells negatively regulated tumor blood flow in response to vasoactive agents in a CD47-dependent manner." (PMID 37958404, 2023). "Pre-clinical studies have confirmed that anti-CD47 enhances the anti-tumor efficacy of anti-PD1/PD-L1, including in melanoma, colon carcinoma, lung cancer, and high-Ep-CAM cancer cells." (PMID 35317832, 2022). "The Fab portion of mAbs can be used to block signaling pathways which promote melanoma growth and survival, for example blocking TAM chemoattractant pathways, blocking immunoregulatory axes such as SIPRα/CD47 and inhibiting immunoregulatory MIF." (PMID 36211808, 2022). "Recent clinical trials have indicated that inhibition of CD47 with anti-CD47 antibodies exerts a promising antitumor effect against several human malignancies, including NSCLC, melanoma, and hematologic malignancies." (PMID 34195295, 2021). "In melanoma cells, the expression of particular molecules, such as colony-stimulator factor 1 (CSF1) or CD47, in response to T-cell derived cytokines represents a conserved and adaptive resistance mechanism involved in disease progression." (PMID 33947438, 2021). "Recent clinical trials have indicated that inhibition of this pathway with anti-CD47 antibodies exerts a promising antitumor effect against several human malignancies, including NSCLC, melanoma, and hematologic malignancies." (PMID 34195295, 2021). "We previously reported that SIRPγ/CD47 blockade inhibits IFN-γ release in human tumor-antigen T-cell cross-priming assays using a CD8+ T-cell clone isolated and expanded from a melanoma patient." (PMID 34925315, 2021). "To assess the ability of NTP to modulate surface CD47 on cancerous cells, we used three different cancer cell types: glioblastoma (U87), head and neck cancer squamous cell carcinoma (SC263), and melanoma (A375)." (PMID 33540720, 2021). "Vaccination with CD47 knockout tumor cells induces CD11c+SIRPα+ DCs activation and enhances T cell response in B16F0 melanoma mouse tumor model." (PMID 34512146, 2021). "Melanoma tumors, established subcutaneously in syngeneic mice, were also treated with NTP, resected, and evaluated for CD47." (PMID 33540720, 2021).
melanoma (continued). "We used the LCS assay to validate and extend these findings by treating A2058 melanoma cells with SEN177 to inhibit QPCTL and block the N-terminal pyroglutamate modification of CD47." (PMID 32240171, 2020). "We previously reported that in melanoma cells, BNIP3 regulates cellular morphology, mitochondrial clearance, cellular viability and maintains protein expression of CD47, a pro-cancerous, immunosuppressive 'don't eat me' signal." (PMID 29707136, 2018). "However, whether melanoma-associated BNIP3 modulates CD47-associated immunological effects or ICD has not been explored properly." (PMID 29707136, 2018). "Furthermore, CD47 expression was upregulated by treatment with vemurafenib in a panel of fresh melanoma isolates carrying the BRAFV600E mutation.Taken together, these results suggest that treatment with BRAF or MEK inhibitors upregulates CD47 expression due to reactivation of ERK." (PMID 29050218, 2017). "The effect of BRAF/MEK inhibitors on the expression of CD47 was confirmed in additional two BRAFV600E (IgR3 and Sk-Mel-28) and two wild-type BRAF (ME1007 and ME4405) melanoma cells lines treated with vemurafenib and trametinib, respectively." (PMID 29050218, 2017). "Another important finding of this study is that NRF-1 is responsible for ERK-mediated constitutive expression of CD47 and its upregulation upon BRAF/MEK inhibitor treatment in melanoma cells." (PMID 29050218, 2017). "In summary, we have shown in this study that treatment with BRAF/MEK inhibitors upregulates CD47 expression through NRF-1, and that this is mediated by reactivation of ERK in melanoma cells." (PMID 29050218, 2017). "While rNDV vectors mediate a functional and localized CD47 blockade that result in improved CD8+ T cell activation, this combination did not result in significantly enhanced APC function or survival in B16-F10 melanoma." (PMID 41322194, 2025). "Furthermore, combining CSPG4-targeting CAR-Ms with strategies inhibiting CD47/SIRPα “don’t eat me” signaling synergistically enhanced CAR-M-mediated phagocytosis and robustly inhibited melanoma spheroid growth in 3D." (PMID 40082557, 2025). "In melanoma, anti-CD47 alone does not induce lasting antitumor immune responses in B16 tumors unless combined with anti-PD-L1, but not anti-CTLA4." (PMID 38414061, 2024). "In summary, our study represents a novel approach to target the CD47/SIRPα axis by controlling the expression of “do not eat me” signals on melanoma cells and macrophages." (PMID 38414061, 2024). "Two phase 1 trials were initiated to study an IgG4 mAb against CD47 in melanoma, which was conjugated to a (not yet fully elucidated) toxin, as a monotherapy and in combination with other immunotherapies including anti-PD-1 (NCT03957096, NCT02890368)." (PMID 36211808, 2022). "TGF-β-expressing B cells in the melanoma tumor microenvironment assembled in clusters and interacted with T cells via lymphoid recruitment (SELL, CXCL13, CCL4, CD74) signals and with Tregs via CD47:SIRP-γ, and FOXP3-promoting Galectin-9:CD44." (PMID 35909944, 2022). "Results suggested that the soluble SHPS-1 ligand (CD47-Fc fusion protein) binds to Melan-a nontumorigenic melanocytes but not to B16F10 melanoma cells." (PMID 34440905, 2021). "CD47 expression was found to be variable among the cell lines tested, suggesting that the difference in engulfment between melanoma and other cancer cells is not attributable to the magnitude of CD47 expression." (PMID 31205227, 2020). "CD47 blockade led to a slight increase in antigen-specific CD8+ T cell activation in vivo, but this was not therapeutically relevant, as CD47 blockade failed to mediate B16 melanoma tumour regression." (PMID 31205227, 2020). "To examine the potential clinical relevance of CD47 upregulation in acquired resistance to BRAF inhibitors in vivo, we took advantage of primary melanoma cell cultures of paired BRAFV600E melanoma biopsy samples from five patients pre- and post-treatment with vemurafenib." (PMID 29050218, 2017).